RNU6-972P (RNA, U6 small nuclear 972, pseudogene)
Gene: Small nuclear RNA gene on chromosome X (136,773,999 to 136,774,105, forward strand). Ensembl gene ENSG00000212510.
Homologues: Orthologues: chimpanzee U6 (100% identical), macaque U6 (94% identical), mouse Gm25039 (81% identical), guinea pig U6 (68% identical). Paralogues in human: RNU6-43P (85% identical), RNU6-238P (84% identical), RNU6-727P (83% identical), RNU6-1020P (82% identical), RNU6-21P (82% identical), RNU6-24P (82% identical), RNU6-255P (82% identical), RNU6-774P (82% identical), RNU6-784P (82% identical), RNU6-11P (81% identical), RNU6-1243P (81% identical), RNU6-1331P (81% identical), and 1286 more.